IL1B (interleukin 1 beta)
Diseases named in the same sentence as IL1B in open-access papers (continued):
Sharing a sentence is not in itself a finding about the gene and the disease.
rheumatoid arthritis (continued). "Abundant evidence has indicated an important role for IL-1β in the pathophysiology of various inflammatory conditions, such as rheumatoid arthritis, as well as prosthetic aseptic loosening of arthroplasty." (PMID 26130370, 2015). "It has been shown that both cigarette smoke condensate (CSC) and polycyclic aromatic hydrocarbons (PAHs) are able to induce interleukin-1 (IL-1β) and tumor necrosis factor α (TNFα) at mRNA and protein levels in the rheumatoid arthritis cells." (PMID 25561937, 2015). "Since pro-inflammatory mediators as tumor necrosis factor-α (TNFα) or Interleukin-1β (IL1β) are elevated in rheumatoid arthritis patients and trigger atherogenesis, the design of new drugs is focusing on the reduction of these inflammatory mediators." (PMID 26076475, 2015). "As a broad-spectrum proinflammatory cytokine, interleukin-1β (IL-1β) is involved in the development of both local and systemic inflammation in rheumatoid arthritis." (PMID 26448682, 2015). "Among the cytokines, two forms of Interleukin-1 (IL-1α and IL-1β) are thought to play an important role in inflammation and involved in many pathological conditions including rheumatoid arthritis." (PMID 24705413, 2014). "The neutralisation of IL-1β signalling appears to be crucial for the potential therapy of osteomyelitis, but also for other inflammatory diseases, such as rheumatoid arthritis." (PMID 24973754, 2014). "IL-1β is a key cytokine and dysregulation can contribute to disorders ranging from metabolic dysfunction to schizophrenia and rheumatoid arthritis." (PMID 23844177, 2013). "Cyclooxygenase (COX) is strongly induced by IL-1β and plays an important role in the pathophysiology of rheumatoid arthritis." (PMID 23442977, 2013). "In diseases such as OA and rheumatoid arthritis (RA) chondrocytes are targeted, via specific cell-surface cytokine receptors, by pro-inflammatory cytokines such as interleukin-1β (IL-1β) and tumour necrosis factor-α (TNF-α)." (PMID 24373218, 2013). "We investigated the ability of SR leaves (SRL) to inhibit in vitro the interleukin-1β (IL-1β)-activated proliferation of synoviocyte-like cells derived from rheumatoid arthritis model mice." (PMID 22537486, 2012). "IL-1β is implicated in rheumatoid arthritis (RA) and enhanced intestinal permeability." (PMID 19622602, 2011). "The expression of TNF-α and IL-1β is especially elevated during an acute phase of rheumatoid arthritis." (PMID 23675204, 2010). "In this study, the anti-inflammatory effects of piperine were tested in IL1β-stimulated rheumatoid arthritis fibroblast-like synoviocytes derived from patients with rheumatoid arthritis." (PMID 19327174, 2009). "The in vitro anti-inflammatory activity of piperine was tested on interleukin 1β (IL1β)-stimulated fibroblast-like synoviocytes derived form patients with rheumatoid arthritis." (PMID 19327174, 2009). "Correlations have been found between plasma IL-1β levels and severity of acute attacks of rheumatoid arthritis, thermal burns, and mortality in septic shock." (PMID 18710581, 2008). "It is believed that locally synthesized IL-1β by synovial cells in inflamed joints plays a key role in the pathogenesis of rheumatoid arthritis, and IL-1β can be used as a marker for evaluating the efficacy of therapeutics for rheumatoid arthritis." (PMID 18710581, 2008). "IL-1β have been found in the synovial fluid recovered from inflamed joints of rheumatoid arthritis patients." (PMID 18710581, 2008). "In fact, IL-1Ra, a blocker of IL-1β transduction, has been administered to patients with septic shock, rheumatoid arthritis, steroid resistant graft-versus-host disease, AML, CML and so on." (PMID 18710581, 2008). "Rheumatoid arthritis (RA) is an autoimmune disease characterized by hyperplasia of the synovial lining, inflammation, high levels of circulating and local IL-1β and tumor necrosis factor (TNF)α, and destruction of cartilage and bone." (PMID 17509138, 2007).
rheumatoid arthritis (continued). "At a concentration of 600 μmol/l, TauCl did not significantly inhibit phosphorylation of mitogen-activated protein kinase or IκB degradation in IL-1β stimulated rheumatoid arthritis FLSs." (PMID 17697361, 2007). "Regulation of the Wnt signalingpathwayin rheumatoid arthritis involves interleukin-1 beta,tumor necrosis factor alpha, and interleukin-6, which activatethe expression of the WNT5A gene encoding the WNT5Aprotein – a ligand of FZD receptors participating in the noncanonicalWnt pathway." (PMID 41536794, 2025). "IL-1β has also been shown to activate PGE2 in synoviocytes in rheumatoid arthritis." (PMID 41009650, 2025). "Similarly, a clinical trial reported PRP was an effective therapy in treating rheumatoid arthritis patients through its down-regulating effect on inflammatory cytokines, such as IL-1β and TNF α." (PMID 39906617, 2025). "For instance, in a study that evaluated the effects of Anakinra (interleukin-1 receptor antagonist) in 80 patients with rheumatoid arthritis on coronary and left ventricular function, the patients with higher IL-1B levels presented the highest reduction in GLS after Anakinra administration." (PMID 38535084, 2024). "Additionally, CA inhibits NLRP3-derived IL-1β production, a critical driver of inflammation in rheumatoid arthritis." (PMID 39684628, 2024). "In this work, 8-shogaol application resulted in significant inhibition of TNF-α-, IL-1β-, and IL-17-mediated inflammation and migration of fibroblast-like synoviocytes derived from rheumatoid arthritis patients (applied at 5 μM and 10 μM) as well as in 3D synovial culture system." (PMID 39199328, 2024). "Interestingly, unlike gypenoside III, rutin significantly improves inflammatory cell infiltration, cartilage and bone erosion, and synovial hyperplasia in rheumatoid arthritis models by lowering IL-1β and TNF-α and inhibiting the NF-κB pathway." (PMID 39273553, 2024). "USP5 can also stabilize TRAF6 by deubiquitination, but contrary to the results of USP3, overexpression of USP5 increases the activation of NF-κB pathway, promotes the release of NF-κB, and then up-regulates the secretion of pro-inflammatory cytokines such as IL-1β in rheumatoid arthritis (RA)." (PMID 40226783, 2024). "Kaempferol reduced the production of matrix metalloproteinases-1 (MMP-1), matrix metalloproteinases-3(MMP-3), COX-2, and prostaglandin E2 (PGE2) in response to interleukin-1β (IL-1β) as well as the proliferation of both unstimulated and IL-1β-stimulated rheumatoid arthritis synovial fibroblasts." (PMID 38496846, 2024). "Similarly, bufalin, a cardiotonic steroid, has been found to reduce cancer cell migration/invasion and IL‐1β‐induced proliferation of rheumatoid arthritis fibroblast‐like synoviocytes by downregulating the expression of MAPK signalling components." (PMID 38044583, 2024). "In addition, cytokines and proteases produced by mast cells are involved in the pathogenic process of rheumatoid arthritis, especially TNF, IL-1β, IL-17, and trypsin-like enzymes." (PMID 39144634, 2024). "Furthermore, in the synoviocytes of mice with rheumatoid arthritis (RA), miR-365-3p was shown to accelerate apoptosis and inhibit cell proliferation by downregulating the expression of IL-1β and IL-6." (PMID 38338832, 2024). "Although the excessive release of IL-1β induces acute inflammation, prolonged local IL-1β production induces the destruction of bones, joints, and blood vessels in chronic inflammatory diseases, such as rheumatoid arthritis." (PMID 37238962, 2023). "Similarly, IL-32β overexpressing mice showed reduced levels of proinflammatory cytokines TNF-α, IL-6, and IL-1β in a murine model of rheumatoid arthritis, which improved arthritic inflammation in these mice." (PMID 37727785, 2023). "In rheumatoid arthritis, miR‐221 was higher in patients with high disease activity, and the reduction of inflammatory cytokines (TNFa, IL‐6, and IL‐1β) by inhibition of miR‐221 suggests that it may be a target for treatment." (PMID 37632245, 2023).
rheumatoid arthritis (continued). "It was also suggested that IL-1β inhibition could represent a broad-acting and efficacious method for managing pain and inflammation across various conditions such as gout, rheumatoid arthritis, or neuropathic pain." (PMID 36233038, 2022). "Various conditions, such as denervation, disuse, aging, rheumatoid arthritis (RA), Crohn’s disease, and cachexia, can cause muscle atrophy, which are all characterized by elevated levels of circulating pro-inflammatory mediators in patients, such as TNFα, IL-1β, and/or IL-6." (PMID 36618945, 2022). "Additionally, canakinumab, a human monoclonal IL-1β antibody, and rilonacept, a decoy receptor of IL-1α and IL-1β, have been targeted in rheumatoid arthritis." (PMID 36387275, 2022). "TNF-α, IL-1β, and IL-6 are mainly involved in acute inflammation, leading to healing, trigger removal, tissue repair, and some systemic autoimmune diseases such as rheumatoid arthritis." (PMID 36613927, 2022). "As the inhibition of IL-1β signaling is important for the treatment of chronic inflammatory diseases, such as osteoarthritis and rheumatoid arthritis, the Type 3 DPIE derivative could be a good framework for anti-inflammatory agents." (PMID 35164164, 2022). "The growing appreciation of the NLRP3 inflammasome activation and bioactive IL‐1β release in acute gouty inflammation or in the more chronic rheumatoid arthritis has prompted studies of agents blocking the IL‐1β receptor or soluble IL‐1β (canakinumab, rilonacept, and anakinra)." (PMID 35438238, 2022). "Additionally, a human monoclonal IL-1β antibody canakinumab, and a decoy receptor of IL-1α and IL-1β rilonacept have been focused on in rheumatoid arthritis." (PMID 35833125, 2022). "IL-1β may also be involved in multiple other diseases that involve MCs, including asthma, rheumatoid arthritis, multiple sclerosis, and psoriasis." (PMID 36362030, 2022). "Anakinra, a targeted IL-1β inhibitor, has been successfully applied to treat rheumatoid arthritis." (PMID 34646239, 2021). "In the monocytes, we found the IL1B+ monocytes (M1) could regulate bone metabolism, and this subtype of monocytes have been reported as a key potential mediator of the pathogenesis of rheumatoid arthritis." (PMID 34111027, 2021). "IL-1β plays a negative role in the pathogenesis of inflammatory-associated bone metabolism diseases, such as rheumatoid arthritis (RA) and bone fractures." (PMID 34976051, 2021). "Theoretically, IL-1β neutralization could also benefit patients with chronic autoinflammatory diseases such as rheumatoid arthritis, as well as type 2 diabetes, which is also considered as a chronic low-grade inflammatory disease." (PMID 34543287, 2021). "Similarly, in vivo, the knockdown of the EP4 receptor reduced circulating levels of IL-1β and IL-6 in a mouse model of rheumatoid arthritis." (PMID 33919366, 2021). "Moreover, similarly to psoriasis, a positive correlation was observed in rheumatoid arthritis [RA] between the levels of IL-23 in serum and synovial fluid of patients and the production of other proinflammatory cytokines, i.e., IL-17, IL-1β or TNF-α." (PMID 33498653, 2021). "MiR-26b has been associated to RA and inflammation where inhibition of miR-26b in rheumatoid arthritis fibroblast-like synoviocytes (RAFLS) causes increased levels of TNF-α, IL-1β, and IL-6, while miR-26b mimics mediate downregulation of the same proinflammatory cytokines." (PMID 33210166, 2021). "However, SNX10 knockout in mice reduces the serum levels of TNF-α and IL-1β, resulting in the suppression of immune inflammation and bone erosion in rheumatoid arthritis." (PMID 33594863, 2021). "Increased NLRP3 expression and activation, together with the release of IL-1β, has been linked to pathogenesis of several painful inflammatory and non-inflammatory conditions such as rheumatoid arthritis, gout, neuropathic pain and diabetic wound healing." (PMID 32973552, 2020).
rheumatoid arthritis (continued). "Moreover, another study showed that blocking of TNF-α markedly reduced the levels of IL-6, IL-1β, and IL-17 in patients with rheumatoid arthritis, indicating that Th17 cell differentiation is promoted by TNF-α through IL-6 and IL-1β." (PMID 33204736, 2020). "Although IL-1β neutralization was once thought to be predominantly limited to the treatment of autoimmune and chronic inflammatory diseases, including gout, rheumatoid arthritis or type 2 diabetes, the role of IL-1β in cardiovascular diseases has gained more and more in importance." (PMID 33216687, 2020). "However, despite that interleukin 1β (IL-1β) has been associated with other autoimmune disorders such as rheumatoid arthritis (RA) and systemic lupus erythematosus (SLE), the association between SNPs in the IL1B gene and IIM has been poorly described." (PMID 33330522, 2020). "Besides, TNFR2 upregulation in rat and human BM-MSCs effectively increased their therapeutic potential in cardiac ischemia and inflammatory disorders like rheumatoid arthritis (RA), which was accompanied by decreased IL-6, IL-1β, and TNFα secretion." (PMID 33344453, 2020). "Several epidemiological, as well as clinical studies, show that androgens attenuate the expression of inflammatory biomarkers including TNF-α, IL-1β, and IL-6 in various chronic inflammatory diseases like Crohn’s disease, psoriasis, rheumatoid arthritis and allergic asthma." (PMID 32120970, 2020). "Interestingly, EVs from the plasma of aged rats show reduced IL-1β levels, which is consistent with the exosome profile in inflammatory condition such as rheumatoid arthritis." (PMID 32859053, 2020). "Furthermore, also the skeletal muscles contribute to an anti-inflammatory milieu, and physical inactivity has been shown to be associated with an increased level of pro-inflammatory muscle markers (IL-1β, IL-6) in rheumatoid arthritis." (PMID 32577833, 2020). "IL-1Ra is a direct inhibitor of IL-1β, and it acts by competing with the cytokines for the binding to IL-1 receptor 1, to the extent that IL-1Ra-based treatments have been developed for rheumatoid arthritis and other autoinflammatory diseases." (PMID 31885616, 2019). "A recent study observed a significant increase of Beclin 1 and LC3-II along with a remarkable decrease of p62 in both IL-1β-stimulated rheumatoid arthritis fibroblast-like synoviocytes and RSC-364 cells after APS treatment, suggesting APS induces autophagy in rheumatoid arthritis." (PMID 30999666, 2019). "Therapeutics targeting IL-1β and IL-1R are approved to treat rheumatoid arthritis; however, all are large proteins with clinical limitations including immunosuppression, due in part to inhibition of NF-κB signaling, which is required for immuno-vigilance and cytoprotection." (PMID 30815434, 2019). "Moreover, cytokines produced in innate immune responses, such as TNFα, IL-6 and IL-1β are found at comparable levels in rheumatoid arthritis joint tissues, early OA and end-stage disease synovium." (PMID 31182934, 2019). "Sclareol not only ameliorated the histological destruction in synovial tissues but also suppressed the activation of the MAPKs and NF-κB translocation induced either by collagen or IL-1β, endowing sclareol with a new pivotal role in the combat of rheumatoid arthritis." (PMID 29751535, 2018). "In addition, TNF-α and IL-1β can trigger NF-κB activation in rheumatoid arthritis and infectious diseases." (PMID 29743895, 2018). "The majority of studies regarding the regulation of molecules for IL-1β signaling have shown that the inhibition of IL-1β signaling is beneficial to hosts with inflammatory diseases such as rheumatoid arthritis, osteoarthritis, and chronic systemic inflammatory conditions." (PMID 29932110, 2018). "In rheumatoid arthritis, IL-6 stimulates the production of inflammatory cytokines by T and B lymphoid cells, promotes the maturation and differentiation of B cells, and enhances the effects of IL-1β and TNFα." (PMID 28953986, 2017).
rheumatoid arthritis (continued). "Moreover, the results presented here support the notion that compound 9 and 15 are active against rheumatoid arthritis and significantly reduce the serum level of Interleukin-1β [IL-1β], cyclooxygenase-2 [COX2] and prostaglandin E2 [PGE2] in the CFA rats." (PMID 29086866, 2017). "In addition, increased expression of IL-6 and IL-8 genes by IL-1β in our study support the inflammatory role of IL-1β as previous in vitro study observing enhanced IL-6 and IL-8 levels in rheumatoid arthritis synovial fibroblasts." (PMID 28068976, 2017). "As a master regulator of pro-inflammatory cytokines such as IL-1β, IL-6 and GM-CSF, over expression of TNF-α causes a variety of chronic inflammatory diseases including rheumatoid arthritis, Crohn’s disease, psoriatic arthritis, ankylosing spondylitis and psoriasis, and so on." (PMID 27658047, 2016). "Moreover, the serum levels of pro-inflammatory cytokines that persist in rheumatoid arthritis including interleukin IL-1β, IL-6 and IL-10 were decreased, although the level changes had not reached statistical significance." (PMID 27658047, 2016). "Furthermore, we know IL-1β perpetuate Th17 responses and endothelial cell damage, which potentiate the rheumatoid arthritis." (PMID 26252209, 2015). "Moreover, Wnt5a overproduction in rheumatoid arthritis was related to the secretion of IL-1β and IL-6 in BMSC." (PMID 24993819, 2014). "Our results suggest that, as in rheumatoid arthritis, the IL-1β- and TNF-α-rich pannus-like tissue may be an invasive tissue involved in the progression of knee osteoarthritis." (PMID 24223987, 2013). "Another anti-inflammatory cytokine secreted by AMs is interleukin-1 receptor antagonist (IL-1ra) which is an endogenous means of protection against inflammatory responses in diseases such as asthma and rheumatoid arthritis by inhibiting the pro-inflammatory mediator interleukin-1beta (IL-1β)." (PMID 22300506, 2012). "Interestingly, HMGB1 potentiates Akt phosphorylation by IL-1β, a pathway involved in cell survival and proliferation of fibroblasts in rheumatoid arthritis synovium." (PMID 20799933, 2010). "Since TNF-α and IL-1β are implicated in arthritis, synovial concentrations of CXCL8 and CXCL10 were compared in patients suffering from crystal arthritis, ankylosing spondylitis, psoriatic arthritis and rheumatoid arthritis." (PMID 16846531, 2006). "The production of tumor necrosis factor α (TNF-α) and interleukin-1β (IL-1β) by monocytes is strongly induced by direct contact with stimulated T lymphocytes, and this mechanism may be critical in the pathogenesis of rheumatoid arthritis (RA)." (PMID 15540281, 2004). "Rheumatoid arthritis (RA): The increased levels of IL-1β, TNFα, and IL-6 which are found in RA also resemble a Trained Immunity phenotype." (PMID 41432375, 2025). "IL-1β-expressing macrophages have been described in rheumatoid arthritis (RA), immune checkpoint inhibitor-induced inflammatory arthritis (ICI-arthritis), and pancreatic cancer and proposed to be pathogenic." (PMID 40662950, 2025). "Several of the induced genes, particularly proinflammatory cytokines IL1β, IL6, and PTGS2 and genes involved in antigen presentation (HLA-DRB1), have been implicated in persistent inflammation in other conditions including atopic dermatitis, psoriasis, and rheumatoid arthritis." (PMID 41333458, 2025). "Canakinumab is a human monoclonal anti-IL-1β antibody, approved for use in cryopyrin-associated periodic syndromes (CAPS) (an IL-1β driven inflammatory disease) and under investigation for use in rheumatoid arthritis, systemic juvenile idiopathic arthritis and refractory gout." (PMID 39286685, 2024). "Downregulation of PVT1 reduces proliferation and IL-1β release while inducing apoptosis of rheumatoid arthritis fibroblast-like synoviocytes (RA-FLS) by mediating the miR-543/SCUBE2 axis." (PMID 39062113, 2024).